NAT10 (N-acetyltransferase 10)
Diseases named in the same sentence as NAT10 in open-access papers (continued):
Sharing a sentence is not in itself a finding about the gene and the disease.
tumor (continued). "NAT10 drives tumor progression and lymphangiogenesis by facilitating the nuclear import of the Yes1‐associated transcriptional regulator (YAP1)." (PMID 39640362, 2024). "We also constructed a tumor metastasis model by injecting NAT10‐knockdown DU145 cells intravenously into the mice to validate the effect of NAT10 on PCa metastasis." (PMID 38922788, 2024). "Targeting NAT10 represents a promising therapeutic approach for overcoming cisplatin resistance and tumor growth of BCa." (PMID 39640362, 2024). "NAT10 K823‐Khib modification was enhanced during tumor metastasis, demonstrating its involvement in tumor biology." (PMID 39640362, 2024). "Subcutaneous tumor formation experiments in nude mice indicated that knockdown of Nat10 significantly inhibited tumor growth." (PMID 39648231, 2024). "First of all, we evaluated the expression of NAT10 in 31 different types of tumours using the TCGA and GTEx datasets." (PMID 36908042, 2023). "Then, we identified 106 genes related to NAT10 by intersecting the differential genes of tumour and normal samples between the high NAT10 expression group and the low NAT10 expression group." (PMID 36908042, 2023). "Upon analysis of the TCGA data and GEO datasets, we observed that NAT10 was significantly upregulated in gastric and other tumor tissues relative to the corresponding normal tissues." (PMID 36609449, 2023). "Tumor growth curves were generated for the different groups, confirming that knockdown of NAT10 restrained tumor formation in nude mice when compared with controls." (PMID 37484809, 2023). "This study proposes a novel mechanism by which NAT10-mediated mRNA ac4C modification regulates tumor metastasis." (PMID 36765042, 2023). "Thereafter, the changes in tumor weight and volume were analyzed and the results revealed that NAT10 silencing inhibited in vivo tumor growth, while this tendency was reversed by FOXM1 overexpression." (PMID 37948132, 2023). "Intriguingly, immunohistochemistry (IHC) analysis showed that the expression of NAT10 was higher in the center of tumor (CT) than in the invasive margin (IM)." (PMID 37328448, 2023). "Impressively, NAT10 knockdown enhanced the efficacy of PD‐L1 blockade‐mediated tumor regression in vivo." (PMID 37818745, 2023). "Importantly, our results confirmed the upregulation of NAT10 protein expression in CCa specimens, and this aberrant upregulation was associated with less favorable clinicopathological characteristics, such as high tumor stage (P<0.05) and lymph node metastasis (P<0.05), in CCa." (PMID 37818745, 2023). "In our HNSCC patient specimens, qRT-PCR and western blot analyses demonstrated that NAT10 expression was higher in tumor tissues than in those of non-tumor tissues." (PMID 37914704, 2023). "Studies have shown that NAT10 can promote tumor metastasis and drug resistance through ERS, but the molecular mechanism is still unclear." (PMID 36765042, 2023). "Together, our data indicated that the hypoxic tumor microenvironment contributes to the upregulation of NAT10 in GC and that NAT10 transcription is regulated by HIF‐1α." (PMID 37328448, 2023). "Analysis of the relationship between HNRNPUL1 and NAT10 expression using the online Tumour Immune Estimation Resource (TIMER) database suggested a tight connection between the gene expression of these two genes." (PMID 37484809, 2023). "In COAD, we identified two RBPs (NAT10 and NOP56) having all four tumor-associated characteristics presented in this study." (PMID 37384253, 2023).
tumor (continued). "In our current study, we first measured the mRNA level of NAT10 in tumor and adjacent normal tissues obtained from LSCC patients through surgical resection." (PMID 37948132, 2023). "Downregulation of NAT10 markedly impaired tumor growth in mice injected subcutaneously with either SiHa or NAT10+/‐ SiHa cells." (PMID 37818745, 2023). "NAT10 is abundantly transcribed in various tumor tissues, including pancreatic 17, prostates 18, bladders 19, stomachs 20, colons 21, liver 22 and is involved in the biological processes of cell proliferation, invasion, and metastasis." (PMID 37484809, 2023). "ESTIMATE analysis further demonstrated that NAT10 upregulation was associated with a lower ESTIMATE score and stromal score in CCa, indicating the pivotal role of NAT10 in regulating tumor immunity in CCa." (PMID 37818745, 2023). "In this study, we identified differentially expressed genes between tumor and normal liver samples that are modified by NAT10-mediated ac4C and determined 21 genes." (PMID 35493106, 2022). "Patients with high levels of NAT10 had developed more heterotypic tumours and were more likely to progress into advanced stages (Stage III + IV)." (PMID 35522942, 2022). "In vitro the tumour‐sphere formation assays also demonstrated that knockdown of NAT10 attenuated sphere formation." (PMID 35522942, 2022). "Thereafter, the analysis of changes in tumor weight and the trends of tumor volume revealed that NAT10 knockdown inhibited tumor growth in vivo, while its overexpression had an opposite effect." (PMID 36522719, 2022). "NAT10, the only known “writer” protein of ac4C, is thought to have vital effects on tumor metastasis and tumorigenesis." (PMID 36360287, 2022). "N‐acetyltransferase 10 (NAT10), a catalytic enzyme involved in the acetylation modification of tRNA, rRNA and mRNA, has been proven to be integrated with a variety of tumours and Hutchinson‐Gilford syndrome." (PMID 35522942, 2022). "We followed to explore the therapeutic potential by targeting NAT10 in MM cells using Remodelin, which is a small molecule inhibitor with the functions of inhibiting NAT10 and sensitizing tumor cells to chemotherapy." (PMID 35978804, 2022). "Consistently, our immunohistochemistry (IHC) results from the tissue microarray samples demonstrated that the expression of NAT10 in tumours was higher than that in para‐tumour tissues." (PMID 35522942, 2022). "The clinical value of NAT10 was estimated according to NAT10 expression pattern based on TCGA data set and the tumor tissue array." (PMID 35522942, 2022). "In accord with the findings in vitro, the staining frequency and intensity of BCL9L, SOX4 and AKT1 decreased significantly in downregulated‐NAT10 xenograft tumours." (PMID 35522942, 2022). "Measurements of the bladder tissues with tumours demonstrated a significant reduction in bladder mass after the deletion of Nat10 in K14+ cells." (PMID 35522942, 2022). "H&E staining of tumour sections showed that wild‐type mice developed a higher grade of malignant tumours when compared to the NAT10‐cKO mice." (PMID 35522942, 2022). "NAT10 protein expression was significantly up-regulated in tumour cells compared to normal epithelial cells in FFPE samples and increased NAT10 protein expression was correlated with poor overall survival of 267 HNSCC patients." (PMID 34362389, 2021). "Tumour cell proliferation, migration, invasion, and G2/S stage promotion were proven to be regulated by NAT10, thus aggravating the progression of HNSCC in the present study." (PMID 34362389, 2021). "NAT10 was mainly located in the nucleus and more highly expressed in the tumour cells than that in normal epithelial cells." (PMID 34362389, 2021). "NAT10 expression affects the prognosis of pan-cancer patients and is significantly correlated with tumor immune infiltration." (PMID 34094911, 2021). "The results show that NAT10 expression has significant positive correlations with tumor purity in 15 types of cancer." (PMID 34094911, 2021).
tumor (continued). "The potential correlations of NAT10 with immune infiltration stages and gene marker sets were analyzed using the Tumor Immune Estimation Resource and GEPIA2." (PMID 34094911, 2021). "We then investigated the potential correlations of NAT10 with immune infiltration stages using the Tumor Immune Estimation Resource2 (TIMER2) and GEPIA2." (PMID 34094911, 2021). "First, as for B cells and macrophage markers, we analyzed the correlations of NAT10 expression in tumor and normal tissues for LIHC and KIRP based on the GEPIA2 database." (PMID 34094911, 2021). "The findings from our study indicate that NAT10 expression affects the prognosis of pan-cancer patients as well as being significantly correlated with tumor-immune infiltration." (PMID 34094911, 2021). "The sensitization of tumor cells to chemotherapy via the cell cycle arrest induced by the inhibition of NAT10 by Remodelin has been demonstrated." (PMID 33425753, 2020). "The further study, particularly the in vivo anti-tumor effect of NAT10 will strengthen its clinical potential as an AML therapeutic drug." (PMID 33425753, 2020). "Further investigations, especially animal experiments, are highly necessary to understand the pathophysiological role of NAT10 in tumor initiation and progression." (PMID 28859621, 2017). "We found that the growth of xenografted tumor derived from NAT10-silenced B16F10 cells was strongly reduced." (PMID 28880216, 2017). "Furthermore, in vivo data showed that anti-Dkk2 antibody (5F8) not only inhibited tumor proliferation and growth, but also notably reversed the acceleration of Nat10-OE tumor growth." (PMID 41542770, 2026). "Additionally, the enhanced tumor-killing effect of CD8+ T cells under Nat10-KO conditions was abrogated by rDkk2 supplementation." (PMID 41542770, 2026). "Multicolor flow cytometry analysis of tumor-infiltrating immune cells revealed that Nat10 deletion markedly increased CD8+ and CD4+ T cell infiltration and modestly elevated the numbers of NK cells and macrophages, whereas the myeloid-derived suppressor cell populations were unaltered." (PMID 41542770, 2026). "Moreover, NAT10 was found to significantly affect the number of metastases and tumor growth following the injection of cancer cells into the tail vein of mice." (PMID 41862454, 2026). "Next, we established an in vitro coculture assay involving OVA-specific OT1 CD8+ T cells (isolated from OT1 transgenic mice) cocultured with OVA-modified tumor cells to evaluate the effect of WT or Nat10-KO tumor cells on the cytotoxic function of CD8+ T cells." (PMID 41542770, 2026). "NAT10 depletion attenuates tumor progression and activates antitumor immunity in CRC allografts." (PMID 41542770, 2026). "Furthermore, 3D coculture systems revealed that Nat10-KO–OVA tumor spheroids exhibited a lower structural integrity and a higher caspase-3 activation compared with WT-OVA controls." (PMID 41542770, 2026). "Moreover, single-cell data from tumor tissues of patients with clinical CRC receiving anti–PD-1 therapy demonstrated that responders exhibited lower NAT10 expression levels." (PMID 41542770, 2026). "Additionally, immunohistochemical staining for Ki67 revealed a reduced proportion of proliferating tumor cells in Nat10cKO tumors, further supporting the tumor-suppressive effect of intestinal Nat10 ablation." (PMID 41542770, 2026). "The role of NAT10 in the tumor immune microenvironment remains unclear, and future research on NAT10's function in this context will be crucial for revealing mechanisms of tumor immune evasion." (PMID 39764566, 2025). "Interestingly, the NAT10/ac4C/FOXP1 axis activity in the lactate‐rich TME further enhances the immunosuppressive properties of tumor‐infiltrating Tregs." (PMID 39764566, 2025). "NAT10 promotes tumor growth by enhancing its expression via ac4C modification." (PMID 41446042, 2025). "We found that tumor cells with higher NAT10 expression had a greater propensity for nerve invasion." (PMID 40119353, 2025).
tumor (continued). "Furthermore, G‐749 is screened and identified as a novel NAT10 inhibitor capable of effectively impeding lysosomal acidification and tumor metastasis by disrupting the NAT10‐Ubiquitin‐specific Peptidase 39 (USP39) interaction." (PMID 40729677, 2025). "The review further discusses therapeutic strategies targeting NAT10, including small-molecule inhibitors and gene silencing approaches, which show promise in preclinical models by suppressing tumor growth, enhancing chemosensitivity, and mitigating inflammatory damage." (PMID 40588654, 2025). "For instance, variations in NAT10 could influence the expression of immune checkpoint molecules, affecting immune evasion and tumor progression." (PMID 39764566, 2025). "Mice xenograft model was used to determine the effect of NAT10 on tumor growth in vivo." (PMID 40344913, 2025). "To further investigate whether the expression of NAT10 in GC cells promotes tumor angiogenesis, we used the conditioned medium (CM) from NAT10 knockdown (shNAT10) or NAT10-inhibited (Remodelin) GC cells to cultivate HUVECs." (PMID 40860183, 2025). "Moreover, the IHC results confirmed that HK2 was consistently regulated by NAT10 in tumor xenograft tissues, organoids, and tissues of MNU-induced GC." (PMID 39990211, 2025). "While most studies on NAT10 have focused on its role in cancer, where it regulates gene expression to promote tumor progression and resistance to therapy, lipid metabolism dysregulation has emerged as one of the most prominent metabolic changes associated with cancer." (PMID 40779453, 2025). "NAT10 might affect tumor cells' responses to immune attacks by regulating RNA acetylation, influencing antigen presentation, or modifying tumor cell metabolic features, which could, in turn, impact the construction and function of the immune microenvironment." (PMID 39764566, 2025). "The H3K27ac modification may activate NAT10-related signaling pathways, promote fatty acid oxidation, and stimulate tumor energy metabolism, ultimately exacerbating tumor cell resistance to EGFR-TKIs." (PMID 41310903, 2025). "Notably, NAT10 was significantly expressed in epithelial cells, T cells, and fibroblasts, with the highest expression observed in tumor epithelial cells." (PMID 41203621, 2025). "Inhibiting NAT10 expression in ESCA cell lines significantly suppresses tumor progression." (PMID 39764566, 2025). "Preliminary research suggests that NAT10 enhances gene expression by stabilizing RNA and regulating biological processes, such as the tumor cell cycle, ferroptosis, and metabolic pathways, all of which drive tumor progression." (PMID 41203621, 2025). "Finally, the effects of NAT10 on specific immune cell subsets within the TME, such as Tregs, tumor-associated macrophages, and MDSCs, remain unexplored and warrant further investigation." (PMID 41203621, 2025). "In vitro experiments demonstrated that NAT10 promotes tumor proliferation, migration, and invasion." (PMID 41408025, 2025). "Furthermore, analysis of data from The Cancer Genome Atlas (TCGA) confirmed that NAT10 was significantly upregulated in diverse types of tumor tissues, including GC." (PMID 39990211, 2025). "Future studies could explore how NAT10 influences tumor ferroptosis through fatty acid metabolism regulation and whether NAT10 reverses drug resistance via ferroptosis pathways." (PMID 40881352, 2025). "Our findings revealed that NAT10 knockdown significantly inhibited HB tumor growth." (PMID 40303290, 2025). "These interactions might influence tumor growth and metastasis through NAT10 regulation and could provide new targets for novel immune therapies." (PMID 39764566, 2025). "Following DNA damage, NAT10 translocates from nucleolus to nucleoplasm, where it actively participates in pathways including cell cycle arrest, thus playing a pivotal role in maintaining genome stability and tumor survival." (PMID 40588654, 2025). "NAT10 is an acetylation enzyme that has been proven to participate in tumor progression." (PMID 40301349, 2025).
tumor (continued). "In addition, the IHC results showed increased expression of NAT10 and KI-67 in the tumor tissues of the NAT10-overexpressing group." (PMID 39990211, 2025). "Furthermore, NAT10 has been identified as a tumor-promoting factor in NPC through its regulation in mRNA ac4C modification and stability." (PMID 40999468, 2025). "However, NAT10‐mediated ac4C acetylation can regulate the drug resistance of certain tumors, providing a basis for targeting NAT10‐mediated ac4C acetylation to improve tumor resistance." (PMID 39764566, 2025). "This raises critical questions: whether there exists an ac4C deacetylase that reverse-regulates this modification network, and whether NAT10 exerts tumor-suppressive functions through maintaining mRNA structural homeostasis of proto-oncogenes." (PMID 40881352, 2025). "Since NAT10 inhibition enhanced the sensitivity to olaparib in cell culture, we compared the effects of the combination of remodelin and olaparib with that of remodelin and olaparib alone on the growth of tumor xenografts in nude mice." (PMID 40606759, 2025). "Moreover, We summarized the outstanding functions and molecular mechanisms of NAT10 in regulating ferroptosis, fatty acid metabolism, glucose metabolism, and tumor immunity." (PMID 39764566, 2025). "Thus, NAT10 is a pivotal regulator of immune evasion, orchestrating an immunosuppressive tumor microenvironment through its control of immune checkpoints and cytokines." (PMID 41316475, 2025). "Notably, analysis of the TCGA database and HB tumor tissue samples revealed a positive relevance between NAT10 and G6PD expression." (PMID 40303290, 2025). "However, previous studies inferred that NAT10 can exhibit tumor-suppressive properties in certain types of cancer." (PMID 41316475, 2025). "Importantly, the authors discovered a lead compound, #7586‐3507, which significantly inhibits NAT10 Khib modification and shows efficacy at low concentrations in vivo tumor models." (PMID 39764566, 2025). "Similarly, in fresh tumor tissues from 28 HCC patients, Western blot (WB) analysis confirmed NAT10 upregulation in tumor tissues relative to paracancerous tissues." (PMID 41476650, 2025). "Therefore, the NAT10/DDX5/HMGB1 axis suppresses T-cell function in the tumor microenvironment, thereby contributing to immunosuppression in NPC." (PMID 41316475, 2025). "As expected, WT NAT10 was able to rescue the primary tumor growth." (PMID 40138393, 2025). "Moreover, we observed that inhibiting NAT10 with Remodelin or shRNA resulted in a significant reduction in hypoxic areas and cell necrosis within tumors, and tumor volumes and weights were effectively reduced compared to their respective negative controls." (PMID 40860183, 2025). "To further investigate if the NAT10-ac4C-ITGB5 axis could promote tumor metastasis in vivo, we generated luciferase-PANC-1 cells and injected the labeled-cells into the tail vein of severe combined immunodeficiency (SCID) mice." (PMID 40119353, 2025). "Patients with PNI exhibited higher NAT10 expression in tumor cells." (PMID 40119353, 2025). "Analysis of 161 PDAC cases from the Clinical Proteomic Tumor Analysis Consortium (CPTAC) database revealed that NAT10 mRNA expression was positively correlated with CDC42, matrix metalloproteinase-9 (MMP9), and Paxillin (PXN), which are expressed upon the focal adhesion pathway activation." (PMID 40119353, 2025). "Notably, NAT10‐2023 treatment significantly reduces intracellular RNA ac4C modification levels and disrupts NAT10‐RNA interactions, leading to suppressed tumor progression." (PMID 41476650, 2025). "Furthermore, using an intraperitoneal metastasis model with HCCLM3‐Luciferase cells, we observed that NAT10 knockdown significantly suppressed metastasis and tumor growth in vivo." (PMID 41476650, 2025). "Notably, NAT10 expression is significantly downregulated in human colorectal carcinomas, and its overexpression suppresses tumor cell proliferation." (PMID 40588654, 2025).